UCHL3 (ubiquitin C-terminal hydrolase L3)
Diseases named in the same sentence as UCHL3 in open-access papers (continued):
Sharing a sentence is not in itself a finding about the gene and the disease.
bladder cancer (1 paper, 2023). "To validate the action of UCHL3 during bladder cancer in vivo, we established an in vivo nude mouse xenograft model via subcutaneous injection with UCHL3-deficient T24 cells and wild-type T24 cells." (PMID 37740194, 2023). "In our work, we revealed that the expression of deubiquitinase UCHL3 was abundant in bladder cancer and associated with poorer clinical outcomes." (PMID 37740194, 2023). "The aim of this study is to elucidate the mechanisms underlying the impact of UCHL3 on the initiation and progression of bladder cancer and to identify potential targets for its treatment." (PMID 37740194, 2023). "To identify the potential mechanism underlying UCHL3-driven malignant behaviors in bladder cancer, we performed RNA-seq analysis using the UCHL3-deficient and WT T24 cell lines." (PMID 37740194, 2023). "As expected, overexpressing UCHL3 favored the proliferative and migratory activity of bladder cancer cells, and UCHL3 depletion caused reduced bladder cancer cell proliferation and migration." (PMID 37740194, 2023). "In addition, Uchl3-deficient mice presented with a higher survival rate than Uchl3fl/fl mice with BBN-induced bladder cancer." (PMID 37740194, 2023). "In addition, our findings revealed that UCHL3 was abundantly expressed in bladder cancer, and this was associated with deleterious clinicopathological features of bladder cancer." (PMID 37740194, 2023). "Additionally, UCHL3 was highly expressed in bladder cancer cells and associated with indicators of advanced clinicopathology." (PMID 37740194, 2023). "In several bladder cancer cell lines, high levels of UCHL3 protein were accompanied by high levels of CTNNB1 protein." (PMID 37740194, 2023). "In line with its oncogenic role in bladder cancer in vitro and in vivo, UCHL3 was amplified in a TCGA cohort of bladder cancer patients via GEPIA software." (PMID 37740194, 2023). "In this study, we discovered that UCHL3 is a novel oncogene in bladder cancer, suggesting it is a promising target against bladder cancer." (PMID 37740194, 2023). "Functionally, UCHL3 positively regulated bladder cancer cell proliferation and migration, and the depletion of UCHL3 resulted in tumor suppression in vitro and in vivo." (PMID 37740194, 2023). "To gain insight into the biofunction of UCHL3 during bladder cancer development and progression, we forced the stable expression of UCHL3 in EJ cells." (PMID 37740194, 2023). "In summary, Uchl3 tends to facilitate bladder cancer progression by stabilizing CTNNB1 and promoting WNT pathway activity in vivo." (PMID 37740194, 2023). "A BBN-induced bladder cancer model was established to assess the effect of vesicular-specific Uchl3 deletion on tumorigenesis." (PMID 37740194, 2023). "We found that the overexpression of UCHL3 boosted bladder cancer cell proliferation, invasion and migration, while the depletion of UCHL3 in bladder cancer cells delayed tumor tumorigenesis in vitro and in vivo." (PMID 37740194, 2023). "In summary, we showed that UCHL3 expression is amplified in bladder cancer and functions as a tumor promoter that enhances the proliferation and migration of bladder cancer cells in vitro and to bladder tumorigenesis and tumor progression in vivo." (PMID 37740194, 2023). "Next, the bladder cancer dataset retrieved from Sanchez-Carbayo 2 and Dyrskjot Bladder 3 was analyzed, and UCHL3 expression was found to be progressively increased with tumor stage." (PMID 37740194, 2023). "In summary, we found that UCHL3 is amplified in bladder cancer and functions as a tumor promoter that enhances proliferation and migration of tumor cells in vitro and bladder tumorigenesis and progression in vivo." (PMID 37740194, 2023). "Moreover, conditional UCHL3-knockout mice and bladder cancer model mice were established for research." (PMID 37740194, 2023). "Similarly, UCHL3 immunohistochemistry with a bladder cancer tissue microarray verified high UCHL3 expression relative to normal tissues." (PMID 37740194, 2023).
bladder cancer (continued). "Having determined the biofunction of UCHL3 in bladder cancer, we assessed its clinical relevance." (PMID 37740194, 2023). "Therefore, our findings strongly suggest that UCHL3 is a promising therapeutic target for bladder cancer." (PMID 37740194, 2023). "Notably, bladder cancer patients with high UCHL3 levels receive a grim prognosis." (PMID 37740194, 2023). "Thus, UCHL3 functions as a tumor promoter during bladder cancer occurrence and progression." (PMID 37740194, 2023). "Therefore, our findings strongly suggest that UCHL3 is a promising target against bladder cancer." (PMID 37740194, 2023). "However, whether UCHL3 is involved in the deubiquitination of CTNNB1 and its role in bladder cancer remain unknown." (PMID 37740194, 2023).
chordoma (1 paper, 2014). Chordomas are rare malignant tumors arising from embryonic remnants of the notochord in axial skeleton. "Most important, differential expression of UCHL3, a gene involved in cell differentiation, was confirmed in the second chordoma cell line U-CH1." (PMID 24503940, 2014). "We identified UCHL3 to be a key player in chordoma cell development due to its up-regulation in the large physaliferous cell phenotype of both tested chordoma cell lines (MUG-Chor1 and U-CH1)." (PMID 24503940, 2014). "Therefore we conclude, that UCHL3 up-regulation in large physaliferous chordoma cells reflects a process of differentiation from small cells to large physaliferous cells." (PMID 24503940, 2014).
colon cancer (1 paper, 2025). "UCHL3 (ubiquitin carboxy-terminal hydrolase L3) is an important transcription factor that promotes progression of colon cancer." (PMID 40843171, 2025). "UCHL3 is positively associated with P. gingivalis infection in colon cancer; treatment of HCT116 cells or NCM460 cells with P. gingivalis significantly increased UCHL3 levels in a dose-dependent manner." (PMID 40843171, 2025).
esophageal carcinoma (1 paper, 2024). A primary or metastatic malignant neoplasm involving the esophagus. "UCHL3 promotes the malignant progression of esophageal carcinoma by influencing CRY2 methylation." (PMID 38965582, 2024).
Flavivirus Infections (1 paper, 2026). Infections with viruses of the genus FLAVIVIRUS, family FLAVIVIRIDAE. "Using activity-based protein profiling during ZIKV and DENV infections, we discovered that UCHL3 is activated upon flavivirus infection." (PMID 42231789, 2026). "This work therefore identifies UCHL3 as a regulator of sfRNA fate between pro-viral and antiviral RNA condensates, identifying a post-translational mechanism governing viral RNA stability and a potential therapeutic target for flavivirus infections." (PMID 42231789, 2026).
Huntington disease (1 paper, 2026). Huntington disease (HD) is a rare neurodegenerative disorder of the central nervous system characterized by unwanted choreatic movements, behavioral and psychiatric disturbances and dementia. "Furthermore, treatment with a small-molecule inhibitor of UCHL3 recapitulated the effects of UCHL3 lowering and attenuated pathological markers in Huntington's disease medium spiny neurons." (PMID 41578740, 2026).
lymph node metastasis (1 paper, 2025). "Chi-square tests further revealed that elevated UCHL3 expression was closely associated with tumor size (P = 0.043), TNM staging (P = 0.028), and lymph node metastasis (P = 0.029)." (PMID 41271634, 2025).
melanoma (1 paper, 2014). A malignant, usually aggressive tumor composed of atypical, neoplastic melanocytes. "Gene expression of UBC12, APPBP1 and UCHL3 in three melanoma cell lines and in melanocytes were analyzed by real-time PCR." (PMID 24765193, 2014). "With the exception of NEDD8 and UCHL3 in the M14 cell line, all the other enzymes, which correlated closely with neddylation, were upregulated in the three melanoma cell lines." (PMID 24765193, 2014).
memory impairment (1 paper, 2018). "Notably, UCHL3 is expressed in the brain and its deletion in mice has been reported to cause neurodegeneration, retinal degeneration, and significant memory impairment." (PMID 29898404, 2018).
renal carcinoma (1 paper, 2024). A carcinoma arising from the epithelium of the renal parenchyma or the renal pelvis. "In renal cancer IHC samples, the infiltration of immune cells in the RCC tumor was also observed expression of UCHL5, similar to that of UCHL3." (PMID 39034372, 2024).
rhabdomyosarcoma (1 paper, 2018). A rare aggressive malignant mesenchymal neoplasm arising from skeletal muscle. "Here, we report that cancer cells overexpressing TDP1, such as rhabdomyosarcoma, are associated with a concomitant overexpression of UCHL3." (PMID 29898404, 2018). "TDP1 overexpression in the topoisomerase therapy-resistant rhabdomyosarcoma is driven by UCHL3 overexpression." (PMID 29898404, 2018). "Depletion of UCHL3 in rhabdomyosarcoma cells markedly accelerated TDP1 turnover, as measured by CHX chase experiments." (PMID 29898404, 2018). "Depletion of UCHL3 in rhabdomyosarcoma cells reduced TDP1 levels and sensitized cells to TOP1 poisons." (PMID 29898404, 2018). "Depletion of UCHL3 was sufficient to reduce TDP1 expression in rhabdomyosarcoma cells to levels comparable to control cells (top) and led to hypersensitivity to the TOP1 poison CPT (bottom)." (PMID 29898404, 2018). "In line with UCHL3 overexpression, immunoprecipitation of endogenous TDP1 revealed lower levels of K48-ubiquitylated TDP1 in rhabdomyosarcoma compared to control cells." (PMID 29898404, 2018). "Consistent with the higher level of UCHL3 in rhabdomyosarcoma, they exhibited lower levels of CPT-induced topoisomerase cleavage complexes (TOP1cc), which were markedly increased upon UCHL3 depletion." (PMID 29898404, 2018). "Inhibiting the proteasome using MG132 led to marked enrichment of K48-ubiquitylated TDP1 in control cells but no impact in rhabdomyosarcoma cells, due to high UCHL3 levels." (PMID 29898404, 2018).
sarcopenia (1 paper, 2026). Progressive decline in muscle mass due to aging which results in decreased functional capacity of muscles. "By using ML algorithms and expression analysis techniques, this study further validated several URGs including CBLB, PSMD6, RNF115, SMAD3, UCHL3 and ZBTB16 as potential markers associated with sarcopenia." (PMID 41560007, 2026).
triple-negative breast carcinoma (1 paper, 2021). An invasive breast carcinoma which is negative for expression of estrogen receptor (ER), progesterone receptor (PR), and human epidermal growth factor receptor 2 (HER2). "Perifosine, a novel UCHL3 inhibitor, reinforces efficacy of PARP inhibitor in the treatment of triple-negative breast cancer via impairing homologous recombination." (PMID 34016790, 2021).
type 2 diabetes mellitus (1 paper, 2025). A type of diabetes mellitus that is characterized by insulin resistance or desensitization and increased blood glucose levels. "The purpose of our study was to investigate the association between rs4885322 single-nucleotide polymorphism (SNP) of the UCHL3 gene and rs11558538 SNP of the HNMT gene with the risk of DR in Greek patients with type 2 diabetes mellitus (T2DM)." (PMID 40002753, 2025).
cancer (31 papers, 2017 to 2026). A tumor composed of atypical neoplastic, often pleomorphic cells that invade other tissues. "They concluded that UCHL3 regulates physiological Tdp1 enzyme levels, with low UCHL3/Tdp1 levels to be associated with neurodegeneration and elevated levels of UCHL3/Tdp1 to be associated with cancer." (PMID 31698852, 2019). "In addition, overexpression of UCHL3 causes tumor cell resistance to cancer treatment by increasing the DNA damage repair ability, whereas UCHL3 deficiency renders cells to be sensitive to this treatment." (PMID 34016790, 2021). "UCHL3 promotes LDHA expression and can be reduced by shFOXM1, and low-expression of LDHA partially reversed the inhibition of aerobic glycolysis induced by overexpression of UCHL3, UCHL3 may be a potential diagnostic and therapeutic target for the treatment of cancer." (PMID 40630951, 2025). "UCHL3 plays a critical role in tumorigenesis, cancer progression and the onset of neurological disorders." (PMID 39985644, 2025). "In conclusion, we identified a cancer-promoting axis (circMTA2/UCHL3/MTA2) in GC progression, which paves the way for us to design and synthesize targeted inhibitors as well as combination therapies." (PMID 38474064, 2024). "UCHL3 is an effective pharmacological target to block AhR-driven signaling during cancer progression." (PMID 37830596, 2023). "As a member of the deubiquitinating enzyme (DUB) family, ubiquitin C-terminal hydrolase L3 (UCHL3) is abnormally expressed in various cancers." (PMID 37740194, 2023). "In various types of human cancers, UCHL3 is overexpressed, so several studies have tried to identify inhibitors of UCHL3 to develop potential cancer therapies." (PMID 37012254, 2023). "Previous reports have indicated the deubiquitinating and protein-stabilizing effect of UCHL3 in several human cancer types and demonstrated its contribution to carcinogenesis." (PMID 36969045, 2023). "Growing evidence demonstrates that high UCHL3 (ubiquitin C-terminal hydrolase L3) activity promotes cancer onset and progression." (PMID 37830596, 2023). "Based on previous documentation on UCHL3 maintaining NSCLC cancer cell stemness by stabilizing AhR protein level via deubiquitination, we then determined AhR protein with immunohistochemistry." (PMID 35918714, 2022). "Ubiquitin C-terminal hydrolase-L3 (UCHL3), an important member of the ubiquitin C-terminal hydrolase family, is involved in DNA repair and cancer development." (PMID 36142702, 2022). "As a deubiquitination, UCHL3 has been suggested to maintain cancer stem-like properties and accelerate tumor cell growth by stabilizing AhR protein." (PMID 35918714, 2022). "While UCHL3 is growing in potential importance relating to its identification as a cancer target, there have been only two small molecule inhibitors reported in the literature." (PMID 35053210, 2022). "In general, these results indicated that UCHL3 promotes cancer stem-like properties via an oncogenic function." (PMID 32546741, 2020). "Taken together, the UCHL3 function in cancer remains controversial, suggesting the roles of UCHL3 is complicated and context-dependent in individual tumor types." (PMID 33585209, 2020). "In this study, we found that UCHL3 is a contributing factor to cancer stem-like properties that promotes tumorigenesis by stabilizing AhR protein degradation." (PMID 32546741, 2020). "UCHL3 enhanced the DNA damage repair mediated by radiotherapy and chemotherapy in cancer cells via binding to tyrosyl DNA phosphodiesterase 1 (TDP1), a chromosome breakage repair related enzyme, and mediating TDP1 deubiquitination." (PMID 32351584, 2020). "A low level of UCHL3 is associated with reduced TDP1 protein levels, causing neurological disease, whereas its overexpression causes higher TDP1 levels in cancer." (PMID 29898404, 2018). "UCHL3 has previously been identified as a potential therapeutic target in cancer." (PMID 41578740, 2026).
cancer (continued). "Porphyromonas gingivalis-induced UCHL3 may promote cancer progression by activating the NF-κB signaling pathway, which is mediated by the substrate protein GNG12, a guanine nucleotide-binding protein involved in various cellular signal transduction pathways." (PMID 41155306, 2025). "Similar effects of UCHL3 on malignancy have been observed in other cancers." (PMID 41271634, 2025). "UCHL3 enhances cancer cell stemness through intermediary receptor molecules like AhR." (PMID 38965582, 2024). "The deubiquitinase UCHL3 is emerging as an important regulator in human cancer." (PMID 38474064, 2024). "Abnormal expression and a dual function of UCHL3 have been described in human cancer." (PMID 36969045, 2023). "miRNA-582-5p directly targeted UCHL3 and inhibited cancer progression." (PMID 37830596, 2023). "UCHL3 has been designated as an important DUB in various cancers and for DNA repair." (PMID 36142702, 2022). "Our results show that UCHL3 in the cytoplasm may play a biological role and that its expression may be increased in human cancers." (PMID 32546741, 2020). "Therefore, UCHL3 overexpression can render cancer cells resistant to DNA damage inducing chemo and radiotherapy, and targeting UCHL3 can sensitize TNBC to radiation and chemotherapy." (PMID 31113933, 2019). "However, targeting UCHL3 to suppress HR repair, which is also often abnormally upregulated in cancer cells, might be a novel approach to treat cancer." (PMID 37012254, 2023). "Therefore, inhibition of UCHL3 activity or UCHL3 phosphorylation may provide new insights in cancer therapy." (PMID 34177595, 2021). "From the cancer point of view, UCHL3 is an attractive “druggable” target and previous efforts focused on developing UCHL3 inhibitors that specifically target UCHL3 in plasmodium falciparum parasite, offering promising selectivity due to structural differences compared to human UCHL3." (PMID 29898404, 2018). "Thus, UCHL3 inhibition may offer a worthy therapeutic opportunity for cancer cells that possess upregulated PDB repair mechanisms, particularly those that exploit this upregulation as a mechanism to resist TOP1 targeting chemotherapy." (PMID 29898404, 2018). "In general, our study reveals an essential role of the circMTA2/UCHL3/MTA2 axis in GC progression, expanding the current knowledge on the molecular mechanism of MTA2-mediated cancer progress." (PMID 38474064, 2024). "There was an evident increase in the levels of LINC00665, UCHL3, AhR and PD-L1, but miRNA-582-5p was downregulated in the tumor tissues derived from LINC00665-overexpressing cancer cells." (PMID 37830596, 2023). "Notably, several reports also indicated that UCHL3 is aberrantly overexpressed in different types of tumors, so caution should be taken when utilizing farrerol, as the farrerol-mediated activation of UCHL3 might be dangerous for cancer patients." (PMID 37012254, 2023). "UCHL3, an important member of the UCH family, plays an important role in the occurrence and development of cancer, DNA damage repair, osteoblast differentiation, and other diseases and life processes." (PMID 36142702, 2022). "Intriguingly, UCHL3, as a member of UCH family, has recently been revealed to be highly expressed in NSCLC, maintaining the cancer stem-like properties through stabilizing the aryl hydrocarbon receptor (AhR) for γ-H2ax." (PMID 35918714, 2022). "In turn, UCHL3 deubiquitinates RAD51 and promotes the binding between BRCA2 and RAD51, which play an important role in DNA damage repair and the resistance of cancer cells to radiation and chemotherapy." (PMID 34177595, 2021). "In summary, this study identifies UCHL3 as a regulator of chromosomal SSB repair by controlling TDP1 proteostasis and highlights it physiological significance in neurological disease and cancer." (PMID 29898404, 2018). "UCHL3, the closest homologue of UCHL1, has an expression pattern similar to UCHL1 in cancers." (PMID 39034372, 2024).